ZC3H13 (zinc finger CCCH-type containing 13)
Diseases named in the same sentence as ZC3H13 in open-access papers (continued):
Sharing a sentence is not in itself a finding about the gene and the disease.
cervical cancer (continued). "Indeed, tumorsphere and colony formation, and Transwell, EdU, and immunofluorescence staining assays showed that ZC3H13 knockdown had a suppressive effect on cervical cancer stemness, chemoresistance, metastasis, and cell proliferation that was reversed by ov-CENPK in HeLa and SiHa cells." (PMID 35418160, 2022). "However, even though the literatures point out the role of TXNDC12 or ZC3H13 in tumors, the prognostic impact through angiogenesis and thus involvement in cervical cancer remains unclear." (PMID 36712973, 2022). "Differential analysis results showed that many m6A-related genes were differentially expressed between cervical cancer tissues and normal tissues, including METTL14, METTL16, ZC3H13, YTHDC1, and YTHDC2." (PMID 36058934, 2022). "YTHDC1 and YTHDF1 have anti-cancer effects in cervical cancer, while ZC3H13, WTAP, HNRNPC, YTHDF3 and VIRMA have tumor-promoting effects in cervical cancer." (PMID 35581263, 2022). "In human cervical cancer tissues, the expression of PD-L1, METTL16, ZC3H13, and YTHDF1 was highly expressed in cervical cancer patients compared with surrounding normal tissues." (PMID 36091006, 2022). "In cervical cancer (CESC), FMR1 and ZC3H13 emerged as key regulators." (PMID 40565233, 2025). "We speculated that low expressed TRPV1 promotes cervical cancer tumorigenesis through YTHDF1/2/3, HNRNPA2B1, YTHDC1/2, ZC3H13, and METTL14 modification." (PMID 36072430, 2022). "ZC3H13 enhanced stemness and chemoresistance via modulation of CENPK mRNA in cervical cancer cells." (PMID 36091006, 2022). "ZC3H13 and YTHDC1 could act as an prognostic indicator in cervical cancer." (PMID 36072430, 2022). "Subsequent gene interaction network analysis indicated that 3 genes (ZC3H13, METTL14, and CBLL1) appeared to serve as network hubs, suggesting that dysregulation of m6A modification by these genes provided major contributions to the development and/or progression of cervical cancer." (PMID 35418160, 2022). "Moreover, we confirmed that ZC3H13 enhanced CENPK expression, supporting the bioinformatic findings of m6A-mediated dysregulation of CENPK and the correlation between ZC3H13 and CENPK in cervical cancer." (PMID 35418160, 2022).
hepatocellular carcinoma (9 papers, 2020 to 2025). A malignant tumor that arises from hepatocytes. "We evaluated the correlation of ZC3H13 with these immune checkpoints in patients with hepatocellular carcinoma using bioinformatics." (PMID 35278064, 2022). "We further analyzed ZC3H13, which was significantly correlated with the prognosis of patients with hepatocellular carcinoma." (PMID 35582419, 2022). "ZC3H13 is a “protective factor” for patients with hepatocellular carcinoma, and patients with low ZC3H13 expression have a poor prognosis." (PMID 35278064, 2022). "Considering the widespread concern of the methyltransferase ZC3H13, researchers have proposed the following views: ZC3H13 is expected to be a marker for evaluating the prognosis of patients with hepatocellular carcinoma." (PMID 35278064, 2022). "Emerging evidences indicate the prognostic significance of m6A regulator ZC3H13 in hepatocellular carcinoma (HCC)." (PMID 35003256, 2021). "In contrast, ZC3H13 expression is downregulated in hepatocellular carcinoma (HCC)." (PMID 40959082, 2025). "In particular, the N6-methyladenosine RNA methylation regulator ZC3H13 could be a candidate as a novel biomarker and therapeutic target for hepatocellular carcinoma." (PMID 35278064, 2022). "To resolve the current controversy concerning the expression level of ZC3H13 in hepatocellular carcinoma, we further clarified whether ZC3H13 could be a prognostic marker to evaluate hepatocellular carcinoma patients." (PMID 35278064, 2022). "However, the expression of ZC3H13 in patients with hepatocellular carcinoma remains controversial, which triggered us to delve into the expression level of ZC3H13 in patients with hepatocellular carcinoma and its regulatory factors." (PMID 35278064, 2022). "However, the role of ZC3H13 in hepatocellular carcinoma remains controversial." (PMID 35278064, 2022). "In addition, ZC3H13 may affect the prognosis of patients with hepatocellular carcinoma by increasing four tumor immune cell (CD4+ T cells, macrophages, neutrophils and dendritic cells) infiltration and thus affecting the prognosis of patients with hepatocellular carcinoma." (PMID 35278064, 2022).
colon carcinoma (8 papers, 2020 to 2024). "Previous studies have demonstrated that ZC3H13 may be a tumor suppressor protein and has somatic mutations in colon cancer." (PMID 34745261, 2021).
glioma (8 papers, 2020 to 2025). A benign or malignant brain and spinal cord tumor that arises from glial cells (astrocytes, oligodendrocytes, ependymal cells). "The expression of ZC3H13 is generally decreased in glioma tissues, which increases the resistance of glioma to TMZ." (PMID 40469294, 2025). "Defined prognostic risk signature: HNRNPC, ZC3H13, and YTHDF2.HNRNPC plays an important role in malignancy and contributes to the development of gliomas.High expression of HNRNPC correlates with a favourable prognosis." (PMID 36831575, 2023). "Unexpectedly, FMR1, EIF3A, and ZC3H13, whose high expressions indicated poor prognosis, were up-regulated in the IDH mutant and 1p19q codeletion gliomas since the two genomic mutations indicated favorable prognoses." (PMID 33240891, 2020). "However, the expression of ZC3H13 is down-regulated in patients with brain and CNS cancer, liver cancer and lung cancer." (PMID 35582419, 2022). "In addition, a prognostic model was constructed using the three genes (ZC3H13, HNRNPC, and YTHDF2) identified by LASSO regression, which stratified the OS of patients with gliomas into high- and low-risk groups." (PMID 33134160, 2020). "Subsequently, the differential analysis showed that, between glioma and normal brain tissue, a variety of m6A-related genes were differentially expressed, including METTL14, METTL16, ZC3H13, YTHDC1, YTHDC2, YTHDF2 etc." (PMID 35559019, 2022). "As is visible in the violin plot, the mRNA expression levels of YTHDF2, YTHDF1, METTL3, RBM15 and HNRNPC were up‐regulated in glioma compared to normal tissues, whereas the expression levels of ALKBH5, WTAP, YTHDC2, ZC3H13 and METTL14, especially of FTO, were decreased in glioma." (PMID 32449290, 2020).
ovarian carcinoma (7 papers, 2019 to 2023). A malignant neoplasm originating from the surface ovarian epithelium. "GSEA analysis demonstrated that the expressions of METTL3, YTHDC1, RBM15B, HNRNPC, IGF2BP2, RBMX, and ZC3H13 were correlated with a higher number of multiple Hallmark pathways in ovarian cancer." (PMID 33225598, 2021). "In ovarian cancer, the expression of ZC3H13 was found to correspond with poor overall survival of patients and the degree of immune infiltration." (PMID 37194218, 2023). "In contrast to its upregulation in cholangiocarcinoma and EC, we found that ZC3H13 acts as a tumor suppressor in HCC, consistent with the findings in breast and ovarian cancer, suggesting functional diversity of ZC3H13 in different tumors." (PMID 35223847, 2022). "For example, the expression of HNRNPA2B1 was positively correlated with the expressions of IGF2BP3, YTHDC1, YTHDF2, RBM15, and ZC3H13 in ovarian cancer." (PMID 33225598, 2021). "HNRNPC, YTHDC2 and ZC3H13 genes were depleted in ovarian cancer." (PMID 34149801, 2021). "The m6A regulators RBM15, ZC3H13, YTHDF1, and IGF2BP1 may cause ovarian cancer immune infiltration." (PMID 37194218, 2023). "This study identified four-DERRG signature (ALYREF, ZC3H13, WTAP, and METTL1) in OC, which was an independent prognostic model for patient stratification, prognostic evaluation, and prediction of response to immunotherapy in ovarian cancer by classifying OC patients into high- and low-risk groups." (PMID 36545327, 2022). "According to the study, IGF2BP2, KIAA1429, and YTHDF1 regulators are highly amplified in OC, and the majority of m6A genes, including METTL3, KIAA1429, HNRNPC, ZC3H13, and IGF2BP2, are upregulated in ovarian cancer tissues." (PMID 37194218, 2023). "We demonstrated four immune infiltration‐related m6A regulators in ovarian cancer, including RBM15B, ZC3H13, YTHDF1, and IGF2BP1." (PMID 33225598, 2021). "In conclusion, m6A RNA methylation regulators are vital participants in ovarian cancer pathology; and IGF2BP1, VIRMA, and ZC3H13 mRNA levels are valuable factors for prognosis prediction and treatment strategy development." (PMID 32950970, 2020). "Consistent with this, we observed a negative correlation in expression between hSecurin and ZC3H13 across multiple cancers including samples from breast, kidney, and ovarian cancer patients." (PMID 30548174, 2019). "Importantly, our data showed that immune cell infiltration levels and various immune gene markers were closely associated with the expression of m6A regulators, suggesting that RBM15B, ZC3H13, YTHDF1, and IGF2BP1 might play the role of immune infiltration‐related m6A regulators in ovarian cancer." (PMID 33225598, 2021).
liver cancer (5 papers, 2021 to 2025). An epithelial or non-epithelial malignant neoplasm that arises from the liver. "When we combined the results of three databases, we found that the ZC3H13 mRNA expression level was downregulated in liver cancer, and the expression level decreased significantly as the tumor grade increased." (PMID 35582419, 2022). "Both databases showed that KIAA1429 mRNA expression levels were upregulated in liver cancer compared with normal tissues, while ZC3H13 mRNA expression levels were downregulated." (PMID 35582419, 2022). "In contrast, m6A writers METTL14 and ZC3H13 inhibit liver cancer progression." (PMID 39967906, 2025). "Survival outcome analysis suggested that significant correlations existed between ZC3H13 downregulation and poor OS and poor RFS in patients with liver cancer, suggesting its role as a tumor suppressor gene." (PMID 35582419, 2022). "In addition to ZC3H13 and METTL14, m6A writers have been shown to be oncogenic factors in liver cancer." (PMID 39967906, 2025). "The Cox risk score and clinical characteristic analysis confirmed that ZC3H13, METTL13, and YTHDF2 could be used as prognostic indicators and even as targets for new treatment of liver cancer." (PMID 34055974, 2021).
melanoma (5 papers, 2020 to 2024). A malignant, usually aggressive tumor composed of atypical, neoplastic melanocytes. "Comparing primary melanoma and metastases, we found that ALKBH5, ELAVL1, FMR1, HNRNPA2B1, HNRNPC, IGF2BP1/2/3, KIAA1429, LRPPRC, RBM15, YTHDC1/2, YTHDF1/3, and ZC3H13 were significantly upregulated in metastases, while RBM15B and METTL3 were significantly upregulated in primary melanoma." (PMID 34993195, 2021).
pancreatic cancer (5 papers, 2021 to 2025). "ZC3H13 (11%), RBM15B (9%), YTHDF1 (8%), and YTHDC1 (6%) frequently occurred genetic mutations in pancreatic cancer." (PMID 34603372, 2021). "For example, ZC3H13 mediates m6A modification of CENPK mRNA to increase translation of PHF10 in a YTHDF1-dependent manner, which in turn inhibits pancreatic cancer." (PMID 38351022, 2024).
prostate carcinoma (5 papers, 2019 to 2024). A carcinoma that arises from epithelial cells of the prostate gland. "Seven m6A methylation-related genes (ALKBH5, FMR1, IGFBP3, RBM15B, YTHDF1, YTHDF2, and ZC3H13) were identified as cross-talk genes between prostate cancer and PD." (PMID 36133437, 2022).
bladder cancer (4 papers, 2021 to 2025). "Conversely, the expression of CNV-deficient m6A modulators of bladder cancer tissues (such as ZC3H13 and WTAP) was reduced." (PMID 34604051, 2021). "As the Writer of m[superscript 6]A regulator genes, METTL3 and ZC3H13 were elevated in bladder cancer." (PMID 34521394, 2021). "In bladder cancer (BLCA), NSUN2, IGF2BP2, YTHDC1, ALKBH5, TRDMT1, and ZC3H13 were identified, with NSUN2—a 5-methylcytosine (m5C) writer—previously shown to promote tumorigenesis and cancer stemness by stabilizing CCND1 mRNA and driving epithelial–mesenchymal transition." (PMID 40565233, 2025).
clear cell renal carcinoma (4 papers, 2020 to 2024). A malignant epithelial neoplasm of the kidney characterized by the presence of lipid-containing clear cells within a vascular network. "The expression of CNV-deficient m6A regulators IGFBP2 and ZC3H13 clear cell renal cell carcinoma was significantly reduced." (PMID 35281520, 2022). "ZC3H13 also has been demonstrated to have prognostic value in other cancer types, such as lung adenocarcinoma, clear cell renal carcinoma, and anal squamous cell carcinoma." (PMID 33251144, 2020). "In addition, ZC3H13 has been identified as an oncogene in kidney clear cell carcinoma." (PMID 36133437, 2022). "However, ZC3H13 had a lower expression level in clear cell renal carcinoma." (PMID 33251144, 2020).
glioblastoma (4 papers, 2020 to 2024). The most malignant astrocytic tumor (WHO grade IV). "A prognostic model has indicated that ZC3H13 levels are positively associated with glioblastoma prognosis, suggesting its potential as a tumor suppressor." (PMID 38474421, 2024). "Furthermore, the knockdown of ZC3H13 has been linked to increased TMZ resistance in Rb1 mutant glioblastoma cells." (PMID 38474421, 2024). "ZC3H13 plays a role in glioblastoma progression through its interaction with the tumor microenvironment." (PMID 38474421, 2024). "Under hypoxic conditions, ZC3H13 expression in microglia is influenced by neuron-derived exosomes, leading to changes in microglial polarization and subsequently affecting glioblastoma progression." (PMID 38474421, 2024). "Recent studies have reported that RBM15 assists ZC3H13 in regulating m6A methylation, which is essential for speeding up the progress of glioblastoma multiforme (GBM)." (PMID 33643384, 2021). "In human, the functional role of ZC3H13 other than interacting with WTAP is poorly understood, although a recent report suggests that mutant ZC3H13 may facilitate glioblastoma progression." (PMID 35236848, 2022).
lung adenocarcinoma (4 papers, 2020 to 2022). A carcinoma that arises from the lung and is characterized by the presence of malignant glandular epithelial cells. "ZC3H13 expression was higher in lung adenocarcinoma, and its expression pattern was the same as that in HCC." (PMID 33251144, 2020). "IL32 and ZC3H13 also play an important role in tumorigenesis and metastasis of lung adenocarcinoma." (PMID 33000861, 2020). "Among these genes, KIAA1429, HNRNPC, YTHDC2, METTL3, WTAP, YTHDC1, and FTO were down expressed in lung adenocarcinoma, RBM15, ZC3H13, YTHDF1, YTHDF2, and ALKBH5 were up expressed." (PMID 32398949, 2020). "Besides, ZC3H13, ALKBH5, YTHDF1, and YTHDF2 were also positively related with each other in lung adenocarcinoma." (PMID 32398949, 2020).
lung carcinoma (4 papers, 2021 to 2024). "The results showed that the expression profiles of eight m6A regulators (ALKBH5, FTO, HNRNPC, METTL14, RBM15, YTHDC1, YTHDC2, and ZC3H13) were significantly different among the three different lung cancer subtypes (P < 0.01)." (PMID 34805165, 2021). "This study revealed that m6A‐related genes significantly contribute to lung cancer, with the expression levels of YTHDF1, YTHDF2, ELAVL1 and ZC3H13 being crucial for predicting and treating lung cancer, providing new therapeutic targets." (PMID 39135292, 2024). "For example, ZC3H13, CBLL1, ELAVL1, and YTHDF1 are differentially expressed in lung cancer tissues, which is significant for predicting and treating lung cancer." (PMID 37938417, 2023).
asthma (3 papers, 2021 to 2024). "An RF model was established to select five candidate m6A regulators (FMR1, KIAA1429, WTAP, YTHDC2, and ZC3H13) from the 21 m6A regulators to predict the occurrence of childhood asthma." (PMID 33763115, 2021). "Moreover, another study on childhood asthma found that m6A regulators also played a crucial role and screened five candidate m6A regulators (FMR1, KIAA1429, WTAP, YTHDC2, and ZC3H13) to predict the risk of childhood asthma." (PMID 35712670, 2022).
breast invasive carcinoma (3 papers, 2020 to 2021). "The cBioPortal database was applied to select the top 200 positively co-expressed genes of METTL14 and ZC3H13 based on the data from Breast invasive carcinoma (TCGA, PanCancer Atlas)." (PMID 33363011, 2020).
cervical squamous cell carcinoma (3 papers, 2021 to 2022). A squamous cell carcinoma arising from the cervical epithelium. "The results of immunohistochemistry (IHC) from HPA database showed that the expression levels of ZC3H13 were significantly higher in cervical squamous cell carcinoma or adenocarcinoma than in adjacent normal tissues." (PMID 36712973, 2022).
COVID-19 (3 papers, 2021 to 2024). A disease caused by infection with severe acute respiratory syndrome coronavirus 2. "One report in the literature found that ZC3H13 is expressed at lower levels in COVID-19 infected individuals as compared to individuals with a non-COVID-19 infection." (PMID 38414855, 2024). "COVID-19 patients with elevated expression levels of CBLL1, METLL16, and RBM15B presented elevated expression levels of ALKBH5 while elevated METTL14 and ZC3H13 expression demonstrated a negative association with ALKBH5." (PMID 35655464, 2022). "Since the “COVID-19-specific gene signature” is derived from direct comparison of COVID-19 versus non-COVID-19 infections, ZC3H13, AMIGO1, and ATL3 under-expressed in COVID-19 equates to higher expression in non-COVID-19 infections." (PMID 33437935, 2021). "One possible interpretation of this under-expression of ZC3H13 and AMIGO1 in COVID-19 that could be investigated in future studies is that this novel virus may be inhibiting their expression to escape the host responses that are otherwise functional for previously circulating viral infections." (PMID 33437935, 2021).
endometrial cancer (3 papers, 2021 to 2023). Primary or metastatic malignant neoplasm involving the endometrium (mucous membrane that lines the endometrial cavity). "ZC3H13 expression was shown to be drastically reduced in endometrial carcinoma tissues in a prior study, and it was found to inhibit endometrial carcinoma cell lines from increasing proliferation and invasion." (PMID 36091006, 2022). "Meanwhile, ZC3H13 or YTHDC1 knockdown promoted the proliferation and invasion of endometrial cancer cells." (PMID 34230220, 2021). "In particular, ZC3H13, YTHDC1, and METTL14 were identified as potential markers for endometrial cancer diagnosis and prognosis." (PMID 34230220, 2021).
gastric cancer (3 papers, 2019 to 2025). A primary or metastatic malignant neoplasm involving the stomach. "In summary, we have demonstrated that ZC3H13 regulates EMT and promotes the malignant phenotype of gastric cancer." (PMID 40774945, 2025).